CXCR4 (C-X-C motif chemokine receptor 4)
Diseases named in the same sentence as CXCR4 in open-access papers (continued):
Sharing a sentence is not in itself a finding about the gene and the disease.
breast carcinoma (continued). "Additionally, blocking of the CXCR4-SDF-1 interaction with a neutralizing antibody in an in vivo model of breast cancer metastasis successfully blocked metastases to the axillary lymph nodes." (PMID 22295241, 2012). "Therefore, CXCR4 signaling is a rational therapeutic target for the treatment of ER-positive advanced breast carcinomas." (PMID 22295247, 2012). "Human breast cancer cells express the chemokine receptors CXCR4 and CCR7." (PMID 22481918, 2012). "Initially, we intended to establish whether c-Met and CXCR4 are also expressed on breast cancer cells in clinically resected tissues." (PMID 22242160, 2012). "Conversely, few studies have been targeted on the role of CXCR4 in feline mammary gland neoplasia, although CXCR4 may have a role in development of mammary carcinoma in cats as in women." (PMID 22417013, 2012). "Furthermore they demonstrated a significant correlation of HER2 and CXCR4 in breast cancer patients, which resulted in a significant worse prognosis." (PMID 23082154, 2012). "Bone cells express high amounts of stromal-derived factor 1 (SDF-1), which may allow for breast cancer cell migration in a CXCR4+-dependent manner." (PMID 22295241, 2012). "In addition, BD inhibits expression of pro-metastastic genes PLAU and CXCR4, in breast cancer xenografts." (PMID 22842551, 2012). "Reduced expression of CXCR4 in metastatic lesions as compared to corresponding primary tumors has been reported in breast carcinoma, and hypothesized to be due to CXCL12-induced internalization and degradation and/or lower microenvironmental HIF-1α levels." (PMID 23249693, 2012). "However, the mechanism of the CXCR4 expression modulated by c-Met-HGF axis to enhance the metastatic behavior of breast cancer cells is still unclear." (PMID 22242160, 2012). "We used a rat breast cancer cell line (MTLn3E) stably co-expressing CXCR4-eGFP and CXCR4-TagRFP, generated by retroviral infection and subsequent single cell sorting by FACS to obtain clonal populations with defined ratios of the two differently tagged receptor molecules." (PMID 22506000, 2012). "Finally, in the primary cultures obtained from 6 primary feline mammary carcinomas CXCR4 expression was detected in all cells and its activation by SDF-1 in vitro treatment caused a significant increase in the proliferation rate in 5 out of 6 tumours." (PMID 22417013, 2012). "The change expression of markers such as C-erbB-2 and/or CXCR4 in breast cancer may reflect the response to primary treatment with anthracyclines or other drugs such as taxanes." (PMID 23046610, 2012). "Our study demonstrates that C-erbB-2 and CXCR4 protein expressions in breast cancer detected by TMAs were high concordance with that of the full sections, demonstrating that reliable results could be obtainable in detecting expressions of protein by TMAs." (PMID 23046610, 2012). "Furthermore, downregulation of CXCR4 through RNA interference or functional blockade using monoclonal antibodies showed a decrease in the invasiveness of breast cancer and melanoma." (PMID 22272201, 2012). "In detail, CXCR4 activity was involved in the oestrogen resistance of breast cancer." (PMID 22417013, 2012). "Moreover, high CXCR4 expression has been related to the metastatic potential of breast cancer cells, since." (PMID 22417013, 2012). "Moreover, the chemokine receptor CXCR4 has been shown to be one of the vital factors for metastasis in breast cancer patients." (PMID 22242160, 2012). "CXCR4 expression is unregulated in some breast cancer cells." (PMID 23181100, 2012). "Thus, we conclude that CB2-specific synthetic cannabinoids that do not possess psychoactivity can be developed to design novel therapies against breast cancer growth and metastasis by blocking CXCR4/CXCL12-induced signaling." (PMID 21915267, 2011).
breast carcinoma (continued). "The E2-induced up-regulation of the chemokine CXCL12 and its receptor CXCR4 and down-regulation of CXCR7 could be associated with the effect of estrogens on the growth of breast cancer cells." (PMID 21695171, 2011). "The role of the CXCR4/CXCL12 axis in breast cancer metastasis has been well documented." (PMID 24212798, 2011). "Thus, we are the first to demonstrate that CXCR4 transcription can be induced by E2 stimulation in breast cancer cells." (PMID 21695171, 2011). "This, together with our previous finding that hypoxia is a feature of basal-like breast cancers, suggests increased Treg infiltration in basal-like cancers may be in part due to hypoxia-induced up-regulation of CXCR4 in Treg." (PMID 21521526, 2011). "However, not much is known about the role of CB2 receptors in modulating CXCR4-mediated effects in breast cancer." (PMID 21915267, 2011). "This hypothesis brings new perspectives to the question about the biology for breast cancer with potential for treatment or intervention using CXCR4-agonists." (PMID 22004990, 2011). "There are reports that CXCR4 may act as a signature gene in contributing to the invasive and metastatic behavior of the breast cancer cells to the brain." (PMID 21673810, 2011). "Several studies have shown how acquisition of the chemokine receptor CXCR4 by breast cancer cells can promote specific, chemotactic recruitment to remote sites such as the bone marrow, lymph nodes, liver and lung in response to localised expression of the specific chemokine ligand, CXCL12." (PMID 24212798, 2011). "Evaluation of breast cancer data present in the Oncomine database indicates that only MMP12 expression is significantly correlated with CXCR4 expression: from the nine breast cancer databases evaluated, the average correlation was 0.31 with an average P value for the correlation of less than 0.04." (PMID 22152016, 2011). "Thus these results suggest that CB2 receptor specific agonists significantly reduced CXCL12/CXCR4-induced migration and invasion of breast cancer cells." (PMID 21915267, 2011). "Interestingly, the NF-κB binding site has also been identified in the proximal region of the CXCR4 promoter and postulated to play a role in CXCR4 expression in human breast cancer cells." (PMID 21880153, 2011). "CAFs can enhance tumor growth in a paracrine manner, with secreted CXCL12 directly stimulating growth of CXCR4 expressing breast cancer cells, and in an endocrine manner, recruiting endothelial progenitor cells (EPCs) to the primary tumors, thus enhancing angiogenesis." (PMID 22152016, 2011). "Furthermore, our studies have revealed that JWH-015 significantly inhibits phosphorylation of CXCR4 and its downstream signaling in vivo in orthotopic and spontaneous breast cancer MMTV-PyMT mouse model systems." (PMID 21915267, 2011). "The goal of this paper is to analyze the literature that has explained the pathways from CXCR4 expression to breast cancer metastasis of the lymph nodes and the prognostic and/or predictive implications of lymph node metastases in the presence of elevated CXCR4." (PMID 22295222, 2011). "Taken together, these observations indicate that enhancement of the expression of CXCL12 and CXCR4 by E2 may constitute a molecular mechanism by which breast cancer cells proliferate in response to that hormone." (PMID 21695171, 2011). "Since these data suggested that IRF5 may contribute to the regulation of CXCR4 in breast cancer cells, we performed a computer-based analysis of the human CXCR4 gene promoter with MatInspector; two IRF binding elements (IRF-E) were identified." (PMID 22053985, 2011). "For example, CXCR4 expression is lower in gastrointestinal tumors than breast cancer." (PMID 22074556, 2011). "Interestingly, a recently published study has shown that women infected with CXCR4-tropic virus had lower breast cancer incidence compared with women with CCCR5-tropic virus." (PMID 21443771, 2011).
breast carcinoma (continued). "In this study we examined the role of cytosine methylation in the regulation of CXCR4 expression in breast cancer cell lines and also correlated the methylation pattern with the clinicopathological aspects of sixty-nine primary breast tumors from a cohort of Brazilian women." (PMID 22220212, 2011). "In this work, we sought to determine whether a modified form of CXCL12, CXCL12(P2G), which acts as an antagonist of CXCR4, is able to block metastasis in the 4T1.2 orthotopic mouse model of breast cancer." (PMID 20849618, 2010). "CXCR4 with its unique ligand SDF1α has been and continues to be a source of investigation into the organ specific metastases of several types of cancer including breast cancer." (PMID 20492653, 2010). "CXCR4 signalling in response to SDF1α induces chemotaxis and migration of breast cancer cells." (PMID 20492653, 2010). "Our hypothesis was that the hypoxia commonly found in primary breast cancers would induce an increased expression of CXCR4, and that this increase in CXCR4 expression would increase breast cancer cells metastatic ability." (PMID 20492653, 2010). "Because the increase in the proliferation of cocultured mammosphere cells induced by SDF-1 was completely inhibited by AMD3100, therapeutic strategies that target SDF-1/CXCR4 may be beneficial to breast cancer patients." (PMID 20569497, 2010). "Further reason to believe that interference with the CXCR4-SDF1α receptor-ligand axis could be of potential therapeutic benefit in the treatment or prevention of breast cancer metastases." (PMID 20492653, 2010). "CXCR4 is expressed on breast cancer cells and exposure to hypoxia upregulated this expression." (PMID 20492653, 2010). "In a landmark study, CXCR4 was shown to be expressed by various human breast cancer cells, and metastasis of these cells in severe combined immunodeficient (SCID) mice could be inhibited with neutralizing CXCR4 antibodies." (PMID 20849618, 2010). "CXCR4 plays an important role in targeting the metastasis of breast cancer." (PMID 20049170, 2010). "However, in the present study, after over 10 years of follow-up observation conducted among 200 breast cancer patients, it was noted that high expression of both cytoplasmic and nucleus CXCR4 often indicated worse prognosis." (PMID 20181250, 2010). "Also used in our studies is an MCF-7 clone (MCF-7/CXCR4) that overexpresses the chemokine receptor CXCR4, a recently described key regulator of breast cancer invasion and metastasis." (PMID 21167057, 2010). "All together, our novel findings suggest that RASSF1C may promote breast cancer cell invasion/migration perhaps in part through the up-regulation of the expression of the CXCR4 gene." (PMID 20955597, 2010). "Although antagonism of CXCR4 is an effective means of inhibiting tumor metastasis, our results highlight the need to consider carefully the merit of using such a strategy as a therapy for breast cancer." (PMID 20849618, 2010). "The fact that CXCR4 is present in normal mammary stem cells suggests that this molecule may be essential for stem cells that appear to be progenitors of breast carcinoma." (PMID 20492653, 2010). "Additionally, CXCR2 and CXCR4 can recruit Gr-1+CD11b+ myeloid cells into invasive front of mammary tumor, an event that directly promotes tumor metastasis." (PMID 20419088, 2010). "While CXCR4 or CXCR7 expression on circulating breast cancer cells increased adhesion to endothelium, CXCL12-dependent enhancements in adhesion or adhesion selectivity were, surprisingly, statistically the same (p = 0.48) and therefore independent of expression of CXCR4 or CXCR7 on cancer cells." (PMID 19484126, 2009). "Furthermore, CXCL12, the ligand for CXCR4, has been shown to be maximally expressed in the organs of metastasis in both lung and breast cancers." (PMID 19563666, 2009).
breast carcinoma (continued). "However, both the OPN and CXCR4 genes can be induced by c-Src, and the induction of an EMT has been associated with the generation of breast cancer stem cells." (PMID 19583841, 2009). "Our results suggest that cytoplasmic CXCR4 expression may be regulated by NO in breast cancer cells." (PMID 19025611, 2008). "Previous study showed siRNA directed against CXCR4 could inhibit breast cancer migration in vitro, but the influence of CXCR4 knockdown on pancreatic cancer was hardly known." (PMID 19002187, 2008). "PGD2 produces similar downregulation of CXCR4 in other celltypes such as the T47D human breast carcinoma cell line (Richard CL, Blay J,unpublished observations), suggesting that this may be a common phenomenon." (PMID 18779872, 2008). "The expression of CXCR4 is lower in lymph node metastases than in primary breast cancer." (PMID 18941460, 2008). "A role of the chemokine/receptor pair CXCL12/CXCR4, normally controlling cell trafficking within the marrow, in the development of solid tumour bone marrow metastases has been shown for small-cell lung cancer, breast cancer, and renal cell cancer." (PMID 18781150, 2008). "Furthermore, metastasis of breast cancer cells to regional lymph nodes and lungs in immunodeficient mice were inhibited by a neutralizing antibody against CXCR4." (PMID 19025611, 2008). "This correlation may become more important as VEGF had been reported to promote breast carcinoma invasion in an autocrine manner by regulating CXCR4, and at the same time CXCR4 promotes VEGF-mediated tumor angiogenesis." (PMID 19025611, 2008). "In this study, we examined how CXCR4 expression relates to nitrotyrosine formation and lymph node metastasis in human breast cancer tissues, and further investigated whether CXCR4 has any value or relevance for predicting disease outcome." (PMID 19025611, 2008). "There is evidencenot only for the use of CXCR4 as a general marker for the progression andmetastasis of breast cancer, but also for the identification of individual tumorcells as they are homing from the primary tumor to secondary sites as patientsdevelop metastatic disease." (PMID 18779872, 2008). "CXCR4 expression was analyzed in primary human breast carcinoma with long-term follow-up." (PMID 19025611, 2008). "NO regulation of CXCR4 expression may play an important role in lymph node metastasis in breast cancer." (PMID 19025611, 2008). "Interestingly, we found that CRC cells had two distinct immunostaining patterns for CXCR4: cytomembrane and nuclear types, similar to those reported in cases of hepatocellular carcinoma, breast cancer, lung cancer, and nasopharyngeal carcinoma." (PMID 18443596, 2008). "Another question of practical importance was whether measurement of cytoplasmic CXCR4 expression has any value or relevance with respect to predicting the disease course in breast carcinomas." (PMID 19025611, 2008). "Indeed, metastatic breast cancer cells have been shown to express high levels of the chemokine receptor CXCR4." (PMID 17726466, 2007). "In breast cancer the prognostic influence of HER2/neu was shown to be at least partly based on increased metastatic potential mediated by the chemokine–chemokine receptor pair SDF-1(CXCL12)/CXCR4." (PMID 17245339, 2007). "Previous studies have shown that heparin is capable of antagonising chemokine function both in vitro and in vivo indicating its potential to disrupt the interaction between CXCL12 and CXCR4, thereby preventing the invasion of CXCR4 expressing breast cancer cells." (PMID 17726466, 2007). "Once the minimum length oligosaccharide was determined, in vivo experiments were designed to investigate the antagonistic effects of these oligosaccharides when compared to polymeric heparin on the haematological metastasis of CXCR4 expressing breast cancer cells." (PMID 17726466, 2007).
breast carcinoma (continued). "Clearly, the activity of the CXCR4 promoter was superior in established breast cancer cell lines, primary breast cancer cells, and primary breast cancer tissue slices, whereas the CXCR4 promoter activity was low in normal breast tissue and, most importantly, human liver." (PMID 16457694, 2005). "However, in patient 4 (advanced, metastatic and recurrent breast cancer after chemo- and radiotherapy), the CXCR4 promoter activity was two-fold higher than the CMV promoter activity." (PMID 16457694, 2005). "Moreover, they demonstrated that neutralization with a specific monoclonal antibody against CXCR4 effectively inhibited the metastasis of breast cancer cells to the lung or lymph nodes in mice." (PMID 15987445, 2005). "Indeed, it has recently been shown that carcinoma-associated fibroblasts secrete CXCL12 and therewith stimulate tumour proliferation directly by acting through CXCR4 found on the breast cancer cells." (PMID 16189523, 2005). "Furthermore, vascular edothelial grwoth factor can also induce CXCR4 expression in breast cancer cells." (PMID 15987445, 2005). "Additionally, CXCR4 may link to G12/13, promoting metastasis in basal‐like breast cancer cells in a RhoA‐dependent manner." (PMID 40969301, 2025). "In addition, the expression of CXCR4 is also increased by the direct effect of transcription factors such as nuclear factor κB (NF-κB), which promotes breast cancer migration and metastasis, or the hypoxia-inducible factor HIF-1α, which promotes dissemination in colorectal cancer." (PMID 40307933, 2025). "Cancer-associated fibroblasts (CAFs) also contribute to the network by promoting TAM recruitment through the CXCL12/CXCR4 axis in breast cancer (BC) and the IL-8/CXCR2 axis in colorectal cancer (CRC)." (PMID 41417432, 2025). "Similarly, silencing the FHC gene increases ROS levels in breast cancer and lung cancer cells, activating the CXCR4/CXCL12 pathway, resulting in the acquisition of an epithelial-mesenchymal transition phenotype and promoting proliferation and migration ability." (PMID 38383702, 2024). "Furthermore, the efficacy and potential side effects of cell surface ‘patching’ to spatially rearrange and antagonize CXCR4 warrant further investigation using transgenic or humanized animal models that closely recapitulate the development of breast cancer metastasis." (PMID 38553476, 2024). "The inhibition of NF-κβ activation reduced the expression of CXCR-4 (a receptor used for breast cancer cell migration) and reduced metastasis in BC cells by preventing epithelial–mesenchymal transition (EMT)." (PMID 38892472, 2024). "En_CXCR4, En_S100A9, and En_PPP1R1B were specifically highly expressed in the angiogenic group, suggesting that these marker genes may be new targets for anti-angiogenic therapy and forebode breast cancer prognosis in the future." (PMID 37626402, 2023). "Also, downregulation of the expression of VEGFR1 and CXCR4 was shown in breast cancer." (PMID 38139334, 2023). "Although anti-CXCR4 therapies are being developed, the value of CXCR4 overexpression in different tumors (as breast cancer, lung cancer, or pancreatic cancer) remains unclear and several studies have provided a non-significant association between CXCR4 expression and clinical outcome." (PMID 37697316, 2023). "However, in the present study, the percentage of patients having CTCs with JUNB expression was higher than those with CXCR4 compared to breast cancer cases, implying that JUNB could be a very important player in metastatic procedure in NSCLC patients." (PMID 36612166, 2022). "In addition, CXCL12/CXCR4 can increase the malignancy of breast cancer and cervical cancer." (PMID 35768705, 2022). "In addition, nanobubbles created by the combination of AMD070 with the light-absorbing material indocyanine green (ICG) were found to block the interaction of CXCL12 with CXCR4 in breast cancer cells, thereby inhibiting the growth of cancer cells and promoting the apoptosis." (PMID 35893797, 2022).